NSUN4 (NOP2/Sun RNA methyltransferase 4)
Diseases named in the same sentence as NSUN4 in open-access papers (continued):
Sharing a sentence is not in itself a finding about the gene and the disease.
tumor (24 papers, 2021 to 2026). "The results uncovered that rapamycin effectively reduced tumor promotion caused by NSUN4 overexpression." (PMID 39634439, 2024). "In conclusion, NOL1 rs3764909 and NSUN4 rs10252 variants are associated with increased ALL tumor susceptibility." (PMID 36698387, 2022). "NOL1 and NSUN4 polymorphisms may be involved in tumor risk-related biological functions by affecting m5C modification of coding and non-coding RNAs." (PMID 36698387, 2022). "Functionally, NSUN4 enhanced tumor cell growth, migration, and invasion while inhibiting ferroptosis." (PMID 42122190, 2026). "Pan-cancer analysis revealed that RNA methylation genes ALYREF, NSUN4, TRMT6, and YTHDF1 were associated with immune infiltration in the tumor microenvironment." (PMID 41244907, 2025). "In the process of differential expression analysis and Cox regression analysis between normal samples and tumor samples in the TCGA database, it was found that NSUN4 was significantly correlated with poor prognosis for HCC patients." (PMID 41180455, 2025). "The western blot was utilized to determine the protein expression level of NSUN4 and mammalian target of rapamycin (mTOR) pathway-related proteins in cells and mouse tumor tissues." (PMID 39634439, 2024). "Four m5C/m6A-related gene signatures consisting of HNRNPA2B1, IGF2BP2, NSUN4, and ALYREF were used to construct a prognostic risk model, and the high-risk group had a worse prognosis, higher immune checkpoint expression, and tumor mutational burden (TMB)." (PMID 36246622, 2022). "In addition, we also analyzed the expression of NSUN members in GSE46602, NOP2 and NSUN2 were highly expressed in tumor tissues, and NSUN4 was lowly expressed." (PMID 35978830, 2022). "The reason may be that advanced tumors require a lot of energy and tumor cells improve their mitochondrial activity and obtain more energy by self-upregulating NSUN4 and other genes." (PMID 34631874, 2021). "Furthermore, NSUN4 had the strongest correlation with CD4+T cells and tumor-associated neutrophils, which is consistent with the results shown in previous studies." (PMID 34195072, 2021). "NOP2, NSUN2, and NSUN4, key RNA m5C methyltransferases, are highly expressed in NSCLC tumour tissue, and their levels are strongly correlated with tumour grade, tumour size, and poor outcomes." (PMID 40860147, 2025). "Among the differentially expressed genes present, DNMT1, NSUN2, NSUN4, and TET2 were highly expressed in LNM + tumor tissues while NSUN5 and NSUN7 expression was reduced." (PMID 37907576, 2023). "Next, we detected the protein expression levels of NSUN4, NSUN7, and DNMT1 via IHC staining in a tissue microarray containing 80 paired normal and tumor tissues." (PMID 36911744, 2023). "In contrast, the expressions of NSUN3, NSUN4, NSUN7, TRDMT1, DNMT1, YBX1, and TET2 were low in tumors and had a tumor-suppressive effect." (PMID 36661693, 2022). "The results revealed significant elevation of NSUN7 and DNMT1 in normal tissues compared with tumor tissues, while NSUN4 showed no obvious difference between the two groups." (PMID 36911744, 2023). "The expression of ALKBH1 (p = 0.036), ALYREF (p < 0.001), NOP2 (p < 0.001), NSUN2 (p < 0.001), NSUN4 (p < 0.001), NSUN5 (p < 0.001), NSUN6 (p < 0.001), NSUN7 (p = 0.006), and YBX1(p < 0.001) were significantly upregulated in tumor tissues compared with the adjacent mucosa." (PMID 35281843, 2022). "On the contrary, in lung squamous carcinoma, while most of the m5C-regulators showed significantly different expression between tumor and normal samples, only NSUN3 could significantly predict prognosis (and NSUN4 almost significantly)." (PMID 36060802, 2022).
tumor (continued). "In this study, we used the TISCH and TIMER databases to analyze the correlation between m5A regulators in LUSC and the six major immune cells in the tumor immune microenvironment, and found that NSUN3 and NSUN4 were expressed to a certain extent in immune cells." (PMID 34195072, 2021). "Using the risk model of m5C regulated genes, it was found that the overexpression of YBX1 gene led to poor prognosis of HCC patients; ALYREF and NSUN4 could also be used as carcinogenic indicators of HCC prognosis and were related to immune infiltration in the tumor microenvironment." (PMID 41180455, 2025). "Having verified that NSUN4 can activate the mTOR signaling pathway, we utilized the CCK-8 experiment and colony formation assay to determine the impact of rapamycin on cell proliferation of cells to further clarify the molecular mechanism of NSUN4 in tumor promotion." (PMID 39634439, 2024). "Moreover, five writers (NOP2, NSUN2, NSUN3, NSUN4 and NSUN5), one reader (ALYREF) and two erasers (TET2 and TET3) were consistently upregulated in UCB tumor tissues compared to adjacent normal tissues from TCGA cohort (fold change > 1.1, P-value <0.05, occurrence rate > 50%)." (PMID 36806253, 2023).
cancer (12 papers, 2019 to 2025). A tumor composed of atypical neoplastic, often pleomorphic cells that invade other tissues. "Mitochondrial translation is disrupted after gene knockout in NSUN4-deficient mice, and research on NSUN3 and NSUN4 in cancer is limited." (PMID 34195072, 2021). "In this risk score signature, four genes (NOP2, NSUN4, NSUN5, and NSUN7) were cancer-promoting and NSUN6 was a cancer-suppressor gene." (PMID 32974125, 2020). "For instance, NSUN1, NSUN2, and NSUN4 were found to be overexpressed in a number of human cancers, including cancer of the breast, gallbladder, bladder, prostate, and cervix." (PMID 32974125, 2020). "NSUN4 participates in cell proliferation and differentiation, protein biosynthesis, and cancer." (PMID 34631874, 2021). "On the contrary, TET2 and NSUN4 showed significant lack of m5C modification related CNV mutations among pan-cancers." (PMID 34325709, 2021). "Existing basic experiments indicate that NOP1, NSUN2, NSUN3, and NSUN4 predominantly promote the majority of cancers, while NSUN5, NSUN6, and NSUN7 demonstrate context-dependent effects—promoting some cancers but inhibiting others." (PMID 41462962, 2025).
mitochondrial disease (2 papers, 2021 to 2025). "To date, only NSUN2, NSUN3 and NSUN4 are known to be involved in methylation of rRNA and tRNAs in mitochondria, and mutations in mt-tRNA m5C RNA writer, NSUN3, are already recognised to cause mitochondrial disease." (PMID 39499421, 2025).
neurological disorders (1 paper, 2023). "NSUN4 and SRRM2 are both involved in neurological disorders; in particular, SRRM2, a splicing factor, regulates ethanol-cue-induced memory in flies." (PMID 37217680, 2023).
NSUN4 also shares sentences with these, for which no sentence is quoted: alcoholic liver diseases (1 paper); cervical cancer (1); cervical squamous cell carcinoma (1); colon cancer (1); colorectal cancer (1); endocervical adenocarcinoma (1); esophageal squamous cell carcinoma (1); gastric cancer (1); infection (1); lung adenocarcinoma (1); malignant glioma (1); mastitis (1); mental retardation (1); neurodegenerative disease (1); renal carcinoma (1); testicular germ cell tumor (1); uveal melanoma (1).